OR7E14P (olfactory receptor family 7 subfamily E member 14 pseudogene)
Synonyms: OR11-5; OR7E151P
Gene: Transcribed unprocessed pseudogene on chromosome 11 (17,052,025 to 17,053,024, forward strand). Ensembl gene ENSG00000184669.
Diseases named in the same sentence as OR7E14P in open-access papers:
OR7E14P is named in the same sentence as 1 disease in open-access papers, as found by Europe PMC text mining. Sharing a sentence is not in itself a finding about the gene and the disease. The quoted sentences say what the papers report.
colorectal cancer (1 paper, 2024). A primary or metastatic malignant neoplasm that affects the colon or rectum. "Few studies have been conducted to investigate the role of the six genes that comprise the 3-GPS (IKBKB-DT, OR7E14P, PLXNA4, LOC401052, RABGAP1, and CTSV) in the context of chemotherapy for colorectal cancer." (PMID 39684481, 2024).